MAP6 (microtubule associated protein 6)
Description:
Involved in microtubule stabilization in many cell types, including neuronal cells (By similarity). Specifically has microtubule cold stabilizing activity (By similarity). Involved in dendrite morphogenesis and maintenance by regulating lysosomal trafficking via its interaction with TMEM106B. Regulates KIF5A-mediated axonal cargo transport (By similarity). Regulates axonal growth during neuron polarization (By similarity).
Synonyms: STOP; KIAA1878; FLJ41346; MAP6-N; MTAP6; N-STOP
Tractability: PROTAC: ubiquitination databases record sites on it; its protein half-life has been measured.
Gene: Protein-coding gene on chromosome 11 (75,586,916 to 75,669,038, reverse strand). Ensembl gene ENSG00000171533.
Subcellular location: Cytoplasm, cytoskeleton; Golgi apparatus; Cell projection, axon; Cell projection, dendrite; Cytoplasmic vesicle, secretory vesicle membrane
Gene Ontology:
Molecular function: protein binding; microtubule binding; calmodulin binding
Biological process: dendrite morphogenesis; lysosome localization; cytoskeleton-dependent intracellular transport; positive regulation of axonogenesis; regulation of microtubule cytoskeleton organization; microtubule cytoskeleton organization
Cellular component: microtubule; perinuclear region of cytoplasm; axon; cis-Golgi network; dendrite; Golgi-associated vesicle; cytoskeleton; Golgi apparatus; transport vesicle membrane
Genetic constraint (gnomAD): Loss-of-function variants: 23 observed, 27.12 expected, observed/expected ratio (o/e) 0.85, 90% interval 0.61 to 1.2. The upper end of that interval is the gene's LOEUF score, 1.2, which puts it in group 5 of 6, group 1 being the genes least tolerant of losing a copy. Missense variants: 908 observed, 892.38 expected, observed/expected ratio (o/e) 1.02, 90% interval 0.96 to 1.08. Synonymous variants: 383 observed, 335.66 expected, observed/expected ratio (o/e) 1.14, 90% interval 1.05 to 1.24.
Homologues: Orthologues: chimpanzee MAP6 (99% identical), macaque MAP6 (92% identical), dog MAP6 (76% identical), pig MAP6 (71% identical), rat Map6 (69% identical), mouse Map6 (68% identical), tropical clawed frog map6 (28% identical), zebrafish map6a (25% identical), zebrafish map6b (23% identical). Paralogues in human: MAP6D1 (9% identical).
Diseases named in the same sentence as MAP6 in open-access papers:
MAP6 is named in the same sentence as 51 diseases in open-access papers, as found by Europe PMC text mining. Sharing a sentence is not in itself a finding about the gene and the disease. The quoted sentences say what the papers report.
schizophrenia (30 papers, 2010 to 2025). A major psychotic disorder characterized by abnormalities in the perception or expression of reality. "Adnp expression is significantly reduced in heterozygous MAP6 (Microtubule-associated) mice used as a model of schizophrenia." (PMID 39485512, 2024). "Mice deficient in MAP6 (STOP) have cognitive, behavioral, and neurobiologic deficits similar to those of schizophrenia patients." (PMID 37153764, 2023). "In fact, knockout of microtubule associated protein 6 (MAP6) in mice results in many similar schizophrenia-like phenotypes as 14-3-3 knockout models." (PMID 35359567, 2022). "As the defects observed in MAP6 KO mice are reminiscent of schizophrenia symptoms, the gold standard treatments for psychiatric diseases were the most obvious approach to try in an attempt to alleviate MAP6 KO deficiencies." (PMID 34025352, 2021). "A reduction of ADNP and its homologous protein, ADNP2, is observed in schizophrenic patients, and it is recapitulated in Map6-deficient (Map6+/−) mice, another transgenic model of schizophrenia." (PMID 30061532, 2018). "As MAP6 KO mouse line is a model for schizophrenia, our work points to a possible muscle weakness associated to some forms of schizophrenia." (PMID 30231928, 2018). "Among the genes that decreased in methylation in the hippocampus is Map6, which is implicated in schizophrenia and is involved in molecular transport, nervous system development and function." (PMID 24382160, 2014). "Abnormal anxiety-like behaviors are found in other animal models of schizophrenia, such as forebrain-specific calcineurin KO, Mus musculus microtubule-associated protein 6 (Mtap6 or STOP) KO, Shn-2 KO, or SNAP-25 KI mice." (PMID 23688147, 2013). "Furthermore, MAP6 expression was upregulated in post-mortem brains of schizophrenia patients, along with two SNPs that showed an association with schizophrenia." (PMID 40589526, 2025). "Interestingly, MAP6-null mice are used as a model of schizophrenia, as microtubules have been implicated in the disorder." (PMID 31969604, 2020). "Moreover, several features of murine models associated with schizophrenia such as anxiety, cognitive deficits, hyperactivity, social impairments and glutamatergic transmission are originated by genetic deletion of MAP6." (PMID 28933765, 2017). "Furthermore, NAP provides protection in the microtubule associated protein 6 (Map6) deficient mouse model of schizophrenia, protecting autophagy and cognitive functions." (PMID 26578950, 2015). "MAP6 mutant mice are a model for schizophrenia and show a reduced presynaptic glutamate vesicle density." (PMID 40589526, 2025). "Single nucleotide polymorphisms (SNPs) and increased mRNA have been identified for MAP6/STOP in the prefrontal cortex of patients with schizophrenia." (PMID 35401110, 2022). "Second, a small peptide motif called NAP—present in Activity-Dependent Neuroprotective Protein (ADNP), which is dysregulated in schizophrenia and in autism —partially alleviates cognitive impairments in MAP6 heterozygous mice." (PMID 34025352, 2021). "The deletion or abnormal expression of MAP6 gene can lead to a variety of diseases, such as schizophrenia and skeletal muscle dysfunction." (PMID 34660263, 2021). "These biological and behavioral defects were shown to respond to long-term treatment with antipsychotics, the gold standard in schizophrenia treatment, thus positioning MAP6 KO mice as a useful model for the study of the physiopathology of this disease." (PMID 34025352, 2021). "Following our seminal 2002 article, numerous studies were performed and their findings reinforced the validity of the MAP6 KO model for the study of schizophrenia." (PMID 34025352, 2021). "We investigated synaptic plasticity defects and behavioral disorders in MAP6 KO mice, an animal model useful for the study of psychiatric disorders, particularly schizophrenia." (PMID 33790791, 2021).
schizophrenia (continued). "The axonal tract defects identified in MAP6 KO mice correlate to a striking extent with anomalies identified on brain images from patients with schizophrenia, including alteration of the fornix or of the cortico-spinal tract." (PMID 34025352, 2021). "It is therefore possible that together with a central nervous system dysfunction, skeletal muscle weakness contributes to the schizophrenia phenotype in the MAP6 KO mice." (PMID 30231928, 2018). "Reflecting the multiple functions of MAP6 proteins at the cellular level, MAP6 null mice (MAP6 KO), which are devoid of all MAP6 isoforms, are viable but display severe behavioral disorders resembling schizophrenia-related symptoms." (PMID 30231928, 2018). "In conclusion, our work emphasizes that MAP6 deletion in mice leads to brain alterations as well as skeletal muscle defects that contributes to the mice schizophrenia-like phenotype." (PMID 30231928, 2018). "The large spectrum of social and cognitive impairments observed in MAP6-KO mice are reminiscent of the symptoms observed in psychiatric diseases, such as schizophrenia, and respond positively to long-term treatment with antipsychotics." (PMID 28871106, 2017). "Genes associated with disease such as MMRN1 (familial parkinsonism), ABAT (autism), and MAP6 (depression and schizophrenia-like symptoms) were also upregulated (for gene functions and references see Suppl." (PMID 23203475, 2013). "MAP6 KO mice were the first animal model to establish a link between cytoskeleton defects and the cognitive impairment characteristics of psychiatric disorders, in particular schizophrenia." (PMID 34025352, 2021). "Indeed, MAP6 KO mice constitutively exhibit behavioral and biological features relevant to some aspects of psychiatric disorders, including schizophrenia and major depressive disorder." (PMID 33790791, 2021). "For example, MAP6 is currently being studied for its role in schizophrenia." (PMID 31289257, 2019). "Moreover, several abnormalities of the MAP6 KO mice were partially reverted using neuroleptics, leading to the proposal of this mouse line as a model for schizophrenia." (PMID 30231928, 2018). "Another MTs regulatory protein involved in schizophrenia is MAP6." (PMID 28933765, 2017). "The MAP6-KO is therefore a relevant model for the study of schizophrenia." (PMID 28871106, 2017). "This suggests that the anatomical changes observed in MAP6-KO mice may account for their schizophrenia-like behavioural and cognitive impairments." (PMID 26037503, 2015). "Indeed, defects in the circuitry connecting the thalamus - which plays a key role in information processing - to the cortex and the cerebellum could explain a number of the schizophrenia-like characteristics of MAP6-KO mice." (PMID 28871106, 2017). "MAP6 (STOP) null mice, which were previously generated by disrupting exon 1 with a cassette containing lacZ and neo genes, are a genetic mouse model of schizophrenia/psychosis." (PMID 37153764, 2023). "Because MAP6/STOP gene knockout female mice demonstrate deficits both in maternal care and behaviors related to the “schizophrenia-like” phenotype, there is a possibility that this gene might also be involved in human maternal care." (PMID 35401110, 2022). "In this study, MAP6 KO mice were used as a model of schizophrenia and the impact of long-term treatment with Pyr1, a LIMK inhibitor and a modulator of MT/actin dynamic, on MAP6 KO mice defects, was analyzed in terms of behavioral, anatomic and physiological parameters." (PMID 33790791, 2021).
Cognitive impairment (5 papers, 2015 to 2023). Abnormal cognition is characterized by deficits in thinking, reasoning, or remembering. "In particular, MAP6 KO (also known as STOP KO) mice display severe behavioural and cognitive deficits, associated with strong impairments in both short-term and long-term synaptic plasticity." (PMID 30224655, 2018). "Interestingly, lower levels of MAP6, a key microtubule stabilizer, have been reported in autistic patients and the deletion of MAP6 produced cognitive defects in mice." (PMID 37035244, 2023). "Future studies assessing these possibilities may provide additional molecular explanations for some of the cognitive impairments observed in MAP6 KO mice." (PMID 34025352, 2021). "Similarly, treatment of MAP6 KO mice with anti-depressants such as fluoxetine/Prozac (a Selective Serotonin Reuptake Inhibitor, gold standard treatment for depression) alleviated anxiety-like behavior and cognitive defects." (PMID 34025352, 2021).
Anxiety (3 papers, 2019 to 2021). Intense feelings of nervousness, tension, or panic often arise in response to interpersonal stresses. "MAP6 KO mice show hyperactivity, fragmentation of normal activity, anxiety-like behavior, social withdrawal, and impaired maternal behavior leading to the death of pups." (PMID 34025352, 2021). "Pyr1 treatment improved synaptic plasticity, and also reduced social withdrawal and depressive/anxiety-like behavior in MAP6 KO mice." (PMID 33790791, 2021). "We subsequently used the Novelty Suppressed Feeding (NSF) test to analyze the severe depressive/anxiety status of MAP6 KO mice that was recently shown to positively respond to non-pharmacological Electro-Convulso-Stimulation (ECS)." (PMID 33790791, 2021).
behavioral disorders (3 papers, 2015 to 2021). "In accordance with the involvement of MAPs in brain disorders, when microtubule-associated protein 6 is deleted in mice (MAP6-KO), severe behavioral disorders are observed, such as locomotor hyperactivity, severe social withdrawal, and cognitive deficits." (PMID 28871106, 2017). "These two geometrical alterations (number and length of fibers) caused the connections between brains areas to form incompletely, an effect which might underline the severe behavioral disorders observed in MAP6-KO mice." (PMID 28871106, 2017). "Fornix disruption in MAP6-KO brains resulted in a disconnection between the hippocampus and the hypothalamus and this impaired connectivity most likely contributes to the observed behavioural disorders." (PMID 26037503, 2015).
psychosis (2 papers, 2021 to 2023). "Indeed, complete deletion of MAP6 drives severe behavioral and functional disturbances mimicking symptoms of psychosis." (PMID 33807989, 2021). "Thus, enhancing A2AR signaling may contribute to the treatment of sleep disorders and psychosis, the latter of which will be studied in MAP6 (STOP) KO mice in the future." (PMID 37153764, 2023).
congenital myopathies (1 paper, 2018). "It is noteworthy that the observed reduction of the mechanical performance in MAP6 KO mice is comparable to that reported in other mouse models for congenital myopathies, arguing that the absence of MAP6 has a direct deleterious impact on muscle function." (PMID 30231928, 2018).
myotonic dystrophy type 1 (1 paper, 2012). Steinert disease, also known as myotonic dystrophy type 1, is a muscle disease characterized by myotonia and by multiorgan damage that combines various degrees of muscle weakness, arrhythmia and/or cardiac conduction disorders, cataract, endocrine damage, sleep disorders and baldness. "Furthermore, in PC12 cells expressing myotonic dystrophy type 1-associated CTG repeats, NGF treatment resulted in reduction in expression of the MT associated proteins MAP6/STOP, while NAP protects against STOP – associated deficiencies." (PMID 23272107, 2012).
osteosarcoma (1 paper, 2020). A usually aggressive malignant bone-forming mesenchymal neoplasm, predominantly affecting adolescents and young adults. "Based on RNA sequencing data, here we report a novel lncRNA, called Lnc-MAP6-1:3, which is highly expressed in osteosarcoma cells." (PMID 32922188, 2020). "We were able to verify that Lnc-MAP6-1:3 is overexpressed in human osteosarcoma tissues and osteosarcoma cell lines." (PMID 32922188, 2020). "Henceforth, Lnc-MAP6-1:3 may provide a new molecular route of research and therapeutic applications for the diagnosis and treatment of osteosarcoma." (PMID 32922188, 2020).
tumor (12 papers, 2014 to 2023). "In consonance with the RNA-Seq results, Lnc-MAP6-1:3 was markedly increased in OS tissues when compared with adjacent non-tumor tissues." (PMID 32922188, 2020). "The results indicated that the transcription level of MAP6 in NSCLC was significantly varied and correlated with advanced tumor stage." (PMID 34660263, 2021). "Of the top 10 survival- genes, only three (MAP6, RIN3, and HIST1H2BI) lacked clear-cut evidence of an oncogenic or tumor suppressor role in the literature." (PMID 26039411, 2015).
cancer (10 papers, 2014 to 2025). A tumor composed of atypical neoplastic, often pleomorphic cells that invade other tissues. "To evaluate a putative function of Lnc-MAP6-1:3 in the cancer cell migration and invasion, we performed transwell assays using OS cells." (PMID 32922188, 2020). "Interestingly, most of these genes are linked with cancer processes (Pld1, Fam13c, Svbp, TMem192, Zc3h7a, RTP4, Naa30, Zgrf1, Slc33a1, Dnmt3b, Map6, Plin4, Eps8L2, Alg12, Capg and Tdp2)." (PMID 37700325, 2023).
psychiatric diseases (5 papers, 2015 to 2021). "To test this possibility, we analyzed the effect of Pyr1 on biological and behavioral defects in MAP6 KO mice (also known as STOP KO mice), a pertinent mouse model used to study psychiatric disorders." (PMID 33790791, 2021).
MAP6 also shares sentences with these, for which no sentence is quoted: infection (7 papers); adenocarcinoma (2); breast carcinoma (2); depression (2); myopathy (2); prostate carcinoma (2); retinitis pigmentosa (2); achromatopsia (1); adenoma (1); alopecia (1); anemia (1); atherosclerosis (1); autism (1); Autoimmunity (1); bladder cancer (1); brain disorder (1); Cachexia (1); colorectal cancer (1); dilated cardiomyopathy (1); frontotemporal dementia (1); gastric adenocarcinoma (1); HCMV infection (1); leukemia (1); liver cancer (1); lung carcinoma (1); medulloblastoma (1); melanoma (1); neuroblastoma (1); Obesity (1); ovarian carcinoma (1).
A further 10 diseases each share a sentence with MAP6 in 1 paper.